LYRM7 (LYR motif containing 7)
Description:
Assembly factor required for Rieske Fe-S protein UQCRFS1 incorporation into the cytochrome b-c1 (CIII) complex. Functions as a chaperone, binding to this subunit within the mitochondrial matrix and stabilizing it prior to its translocation and insertion into the late CIII dimeric intermediate within the mitochondrial inner membrane.
Synonyms: C5orf31; MZM1L; FLJ20796; MC3DN8
Tractability: PROTAC: ubiquitination databases record sites on it; its protein half-life has been measured.
Gene: Protein-coding gene on chromosome 5 (131,170,918 to 131,205,428, forward strand). Ensembl gene ENSG00000186687.
Subcellular location: Mitochondrion matrix
Pathways (Reactome):
Metabolism: Complex III assembly
Gene Ontology:
Molecular function: protein binding; protein folding chaperone
Biological process: cellular respiration; mitochondrial respiratory chain complex III assembly; protein folding
Cellular component: mitochondrial matrix; mitochondrial membrane; mitochondrion
Genetic constraint (gnomAD): Loss-of-function variants: 1 observed, 1.01 expected, observed/expected ratio (o/e) 0.99, 90% interval 0.26 to 1.89. That is too few expected variants to judge how well the gene tolerates losing a copy. Missense variants: 22 observed, 11.62 expected, observed/expected ratio (o/e) 1.89, 90% interval 1.26 to 1.97. Synonymous variants: 6 observed, 4.74 expected, observed/expected ratio (o/e) 1.27, 90% interval 0.66 to 1.89.
Gene-disease validity (ClinGen):
ClinGen rates the evidence that LYRM7 causes each of these diseases.
mitochondrial disease (autosomal recessive): Definitive.
Homologues: Orthologues: chimpanzee LYRM7 (100% identical), macaque LYRM7 (95% identical), rabbit LYRM7 (94% identical), dog LYRM7 (93% identical), guinea pig LYRM7 (92% identical), pig LYRM7 (92% identical), mouse Lyrm7 (84% identical), rat Lyrm7 (84% identical), tropical clawed frog lyrm7 (67% identical), zebrafish lyrm7 (61% identical).
Diseases named in the same sentence as LYRM7 in open-access papers:
LYRM7 is named in the same sentence as 10 diseases in open-access papers, as found by Europe PMC text mining. Sharing a sentence is not in itself a finding about the gene and the disease. The quoted sentences say what the papers report.
breast carcinoma (1 paper, 2022). "High amplification of LYRM7 was associated with breast cancer immune cell infiltration." (PMID 36171887, 2022).
mitochondrial disease (2 papers, 2020 to 2025). "Similarly, pathogenic mutations in the human LYRM7 (MZM1L) are associated with early-onset mitochondrial disease and severe isolated CIII deficiency." (PMID 32481479, 2020). "Late detection of assembly factors with severe phenotype includes genes such as NDUFAF3, SURF1, TACO1, SCO1, LYRM7, or TIMMDC1, whose mutations are commonly found in patients with mitochondrial diseases (Fig. EV2F)." (PMID 40301572, 2025).
cardiovascular disease (1 paper, 2024). "In terms of relating these sex-biased proteins to cardiovascular disease risk, among the proteins shared between both groups, only a limited number have been previously linked to vascular disease in vascular smooth muscle cells, and these (PUDP and LYRM7) were only upregulated in females (6.25%)." (PMID 39796045, 2024).
LYRM7 also shares sentences with these, for which no sentence is quoted: Encephalopathy (3 papers); lactic acidosis (2); alcohol dependence (1); HIV-1 infection (1); infection (1); Obesity (1); tumor (1).